CD4 (CD4 molecule)
Diseases named in the same sentence as CD4 in open-access papers (continued):
Sharing a sentence is not in itself a finding about the gene and the disease.
Opportunistic infection (continued). "For 2 years after his first appointment at our office, he was followed every 4 weeks with close monitoring for any opportunistic infections and every 2 to 3 months with laboratory evaluation for CD4+ and CD8+ counts." (PMID 25528459, 2014). "As a result, he was placed on Bactrim® (trimethoprim-sulfamethoxazole) prophylaxis to prevent opportunistic infections, and his CD4+ and CD8+ counts were monitored over the course of 8 years." (PMID 25528459, 2014). "Median CD4 count for patients with active CMVR at the time of RD was lower than patients with inactive CMVR, consistent with higher risks of opportunistic infections in patients with lower CD4 count levels." (PMID 25429876, 2014). "The lowest levels of Vδ2 cells were found in patients with opportunistic infections or CD4 T cells < 200 cell/mm3 of blood." (PMID 25688241, 2014). "Opportunistic infections rarely occur in acute HIV infected patients who are in a transient CD4+ lymphocytopenia state." (PMID 25160905, 2014). "The 14 HIV positive pregnant women with CD4 count <200/μl continued on daily CTX according to the National guidelines for prevention of opportunistic infections in HIV infected pregnant women." (PMID 24830749, 2014). "According to reports from observational databases, classic AIDS-defining opportunistic infections (ADOIs) occur in patients with CD4 counts above 500/μL on and off cART." (PMID 25394125, 2014). "Although protein S deficiency is not correlated with HIV disease severity it appears that thrombosis is highly correlated with low CD4 counts, the presence of opportunistic infections, malignancies, or autoimmune disorders." (PMID 24570775, 2013). "Non-adherence to HAART also leads to failure to prevent further viral destruction of the cellular immune system with consequent reduction in the level of CD4+ cells and the development of opportunistic infections." (PMID 24052890, 2013). "Socio-demographic characteristics, CD4 T cell count, presence of opportunistic infections at the time of ART initiation and ART regimen intake and survival status was collected periodically." (PMID 23825577, 2013). "Opportunistic infection, CD4 count <200 cells/μl and rural residence in HAART naïve patients; HAART regimen and duration of HAART in HAART experienced patients were identified as risk factors for anemia." (PMID 23977253, 2013). "In the HIV-positive patient CM is a late opportunistic infection usually observed when the T lymphocyte CD4+ cell count falls below 50–100/μL; two-thirds of patients had less than 50 CD4+ cells/μL and the median value reported in several series is below 30/μL." (PMID 24052889, 2013). "There were imbalances in the three groups’ baseline characteristics, such as age, sex, previous history of major opportunistic infections, baseline CD4 cell count, frequency of ARV administration, and history of EFV-based regimen interruptions." (PMID 23347647, 2013). "Opportunistic infections, CD4 count <200 cells/μl and rural residence were identified as the predictors of anemia in HAART naïve participants." (PMID 23977253, 2013). "The most frequent risk factors for the development of IRIS found in the majority of studies were starting CART close to the treatment of opportunistic infection, a low CD4 cell count, and a high viral load." (PMID 23691377, 2013). "Episodes of opportunistic infections among patients taking ART with undetectable VL were associated with elevation of HIV RNA VL to detectable levels and decline in CD4+ T cell counts." (PMID 23547778, 2013). "The variables; age, sex, residence, BMI, intestinal parasitosis, CD4 count, presence of opportunistic infections, HAART regimen, duration of HAART were included in the analysis." (PMID 23977253, 2013). "A sustained immunologic response was observed, with most patients experiencing CD4 recovery above 200 cells/μL, a clinically meaningful threshold for clinical progression and opportunistic infections (OI)." (PMID 24376569, 2013).
Opportunistic infection (continued). "Presence of opportunistic infections (P = 0.004, 95% CI = 1.69–15.46), CD4 count <200 cells/μl (P = 0.001, 95% CI = 2.57–36.89) and rural residence (P = 0.03, 95% CI = 1.12–10.39) were found to be predictors of anemia for HAART naïve participants." (PMID 23977253, 2013). "The reasons for ART initiation were 45 (75.0%) CD4 <300 cells/mL; 31 (51.7%) RNA >50,000 copies mL; and 3 (5.0%) an opportunistic infection." (PMID 24006958, 2013). "For both optimal and continuous treatment the outcome of the opportunistic infection is correlated more to the level of provirus than to the level of CD4+ lymphocytes." (PMID 22558348, 2012). "The majority of patients present with unusual manifestations of opportunistic infections, most often while the number of CD4+ cell count is increasing and/or the plasma HIV RNA level is decreasing." (PMID 22289885, 2012). "Fourteen percent had an initial CD4 count ≤200 cells/mL, requiring prophylaxis for opportunistic infections; 24% had an initial CD4 count of 201–350 cells/mL and 26% had a CD4 count of 351–500 cells/mL." (PMID 22662177, 2012). "age, gender, hemoglobin, body-mass-index (BMI), baseline CD4 cell counts, presence of opportunistic infections (OI) and antiretroviral therapy regimen on overtime change in CD4 cell counts and CD4 cell restoration at 12 and 30 months." (PMID 22348047, 2012). "Apparently, these paradoxical events result from the abnormal expansion of selective CD4+ T cell clones targeting antigens of previous opportunistic infections." (PMID 22411458, 2012). "Those patients with advanced WHO clinical stage had higher likelihood of having TB and other opportunistic infections as it is seen in CD4+ lymphocyte count." (PMID 22738361, 2012). "Overall, among these mothers who presented after delivery, 17 (47.2%) subsequently started ART because of low CD4 counts or concomitant opportunistic infections." (PMID 22558455, 2012). "Once enrolled in HIV care, patients should be staged with clinical and psychosocial evaluation in addition to CD4 count testing to assess eligibility for antiretroviral therapy, and to screen and prophylax for opportunistic infections." (PMID 23176556, 2012). "The CD4+ T-lymphocyte is the primary cellular target of HIV, and theabsolute CD4+ T lymphocyte count is a reliable determinant ofdisease progression and opportunistic infection risk among HIV-infected persons." (PMID 22970105, 2012). "This increase of immunoregulatory CD4+CD25+FoxP3+ T-cells (Treg) during chronic HIV infection disables the immune system’s control over viral replication as well as opportunistic infections." (PMID 22859956, 2012). "As CD4+ lymphocyte count decreased the body defense mechanism will be overwhelmed by various opportunistic infections." (PMID 22738361, 2012). "Survival analysis using endpoints of death, opportunistic infection (OI), and CD4<200 cells μL, and linear mixed models estimating rate of change of HIV-1 RNA and CD4, were used to determine associations between HSV-2 serostatus and HIV-1 progression." (PMID 21637835, 2011). "A multivariable Cox proportional hazards mortality model was developed using the following covariates: weight-for-age Z-score, chronic diarrhea, hemoglobin, CD4%, tuberculosis coinfection, presence of opportunistic infection, age <3 years, and gender." (PMID 21829487, 2011). "Here we report the mortality in hospital and non-hospital settings in a systematically followed cohort of HIV infected individuals by demographic factors, ART status, opportunistic infections and the levels of immunosuppression represented by CD4 counts." (PMID 21537095, 2011). "Measurements included anthropometry; body composition indicators; CD4 count, haemoglobin and albumin; as well as incidence rates of opportunistic infections; depression and quality of life scores." (PMID 22192583, 2011).
Opportunistic infection (continued). "Successful treatment results in virologic suppression, a quantitative increase in the number of CD4+ T cells, and improvement in the clinical well-being of the individual, manifesting as weight gain and resolution or control of opportunistic infections." (PMID 21490777, 2011). "For this purpose we correlated iATP vs. total CD4+ cell counts in n = 286 samples - apart from patients with opportunistic infections - consisting of healthy controls, MS patients devoid of immunomodulatory therapies and MS patients with natalizumab treatment." (PMID 21533133, 2011). "This is the first report of an opportunistic infection with CD4 T-lymphocytopaenia in Chikungunya fever." (PMID 20205786, 2010). "We found a significant inverse correlation between opportunistic infection and a decline in CD4 cell count." (PMID 20300416, 2010). "Those supplemented daily with zinc (45 mg) for 30 days experienced, at follow-up, a lower frequency of opportunistic infections after 24 months and an increase in CD4 count after four months (compared to the controls)." (PMID 22254046, 2010). "Epidemiology and the comorbidities were the primary objectives and as a secondary outcome we found a statistically significant relation between the CD4 cell count and the incidence of opportunistic infection." (PMID 20300416, 2010). "In this report, complementary and clinical examinations detected low CD4 levels, high viral loads, and two or more kinds of opportunistic infection in all three patients though they were persistently indeterminate on the Western blot assays." (PMID 20230617, 2010). "Effective highly active antiretroviral therapy (HAART) reduces human immunodeficiency virus (HIV) replication, restores CD4+ T lymphocyte counts and greatly reduces the incidence of opportunistic infections." (PMID 20500844, 2010). "When effective, HAART increases CD4+ T lymphocyte counts, reduces opportunistic infections and according to early studies, normalizes immune responses." (PMID 20500844, 2010). "Opportunistic infections and KS are rare at CD4 levels >200 and indeed most cases of PCP occur at CD4 counts below 100, along with Mycobacterium avium complex (MAC), fungal infections and CMV." (PMID 20981180, 2010). "Primary endpoint was ART treatment failure determined by plasma HIV RNA level, CD4+ cell count decrease, death attributed to study participation, or opportunistic infection." (PMID 20442758, 2010). "Highly active antiretroviral therapy produces a significant decrease in HIV-1 replication and allows an increase in the CD4 T-cell count, leading to a decrease in the incidence of opportunistic infections and mortality." (PMID 19538732, 2009). "We found that about a third of the opportunistic infections occurred among patients with SO-CD4 reconstitution as defined by either the CD4 increase or the threshold criteria." (PMID 18957083, 2008). "CD4+ lymphopenia was seen in 60% of patients, leading to opportunistic infections as well as other infections indicative of T-cell dysfunction." (PMID 22275974, 2008). "In the Swiss cohort, suboptimal responders had a 1.5 fold higher incidence of opportunistic infections than the complete CD4 responders." (PMID 18957083, 2008). "For several common opportunistic infections, it is considered safe to discontinue preventive antibiotics after a patient's total CD4+ cell count has returned to normal levels on HAART." (PMID 17388662, 2007). "Visceral disease (VL) is the clinical form of leishmaniasis that has the most substantial geographical overlap with HIV and typically occurs as an opportunistic infection among HIV-infected individuals with CD4 cell counts < 200 cells/μL." (PMID 17042934, 2006). "This study aimed to characterize discordant treatment classifications, evaluate immune imbalance using the CD4/CD8 ratio, identify associated clinical predictors, and assess opportunistic infection burden in a Romanian cohort of people living with HIV receiving long-term cART." (PMID 42198715, 2026).
Opportunistic infection (continued). "The possible explanation might be that patients with a low or very low CD4 count are more likely to have different opportunistic infections, and the added burden of diseases further complicates their treatment responses." (PMID 41525305, 2026). "Also, about 1 in 7 respondents had at least one opportunistic infection, 3 in 5 had low CD4 counts, and 56% of respondents had been on ART for over 5 years." (PMID 39743519, 2025). "While hypogammaglobulinaemia accompanied by lymphopenia, particularly CD4+ T-cell lymphopenia, opportunistic infection such as Mycobacterium tuberculosis, pneumocystis jirovecii pneumonia, cytomegalovirus, varicella-zoster virus (VZV) and BK virus can occur with an increased rate." (PMID 41187120, 2025). "Sarcopenia risk, according to the SARC-F, was 27.6 % and was associated with socioeconomic status (p = 0.004), smoking (p = 0.001), disease status (p < 0.001), opportunistic infections (p = 0.001), CD4 T-cell count (p < 0.001), Handgrip Strength (HGS) (p < 0.001), and Gait Speed (GS) (p = 0,001)." (PMID 39752996, 2025). "Moreover, the decrease in CD4 counts is correlated with the decrease in the immunity of patients exposing them to opportunistic infections, which are important factors in the distribution of micronutrients, which in this case is iron." (PMID 40809818, 2025). "This disproportionate burden underscores the importance of understanding the virus's pathogenesis—HIV primarily targets CD4+ T lymphocytes, progressively impairing immune function and rendering individuals vulnerable to opportunistic infections and malignancies." (PMID 40989801, 2025). "As such, when they noted weight loss in a PLHIV attending for HIV care, they reported that they would usually or ideally check the PLHIV’s viral load, CD4 count, investigate for TB and other opportunistic infections, screen for cervical cancer, and test for diabetes." (PMID 40982432, 2025). "Additionally, poor adherence to ART fails to prevent further viral destruction of the cellular immune system, resulting in a decline in CD4+ cell levels and the development of opportunistic infections." (PMID 40182420, 2025). "Compared to females, males were older (median age 36 vs. 30 years, p < 0.001), had lower BMI (median 20.2 vs. 22.3 kg/m2, p < 0.001), lower CD4 counts (median 139 vs. 183 cells/μl, p < 0.001), and were more likely to report a history of prior opportunistic infection (46.2% vs. 39.1%, p = 0.01)." (PMID 40169948, 2025). "This may be because the individuals included in this study were all inpatients and had relatively low CD4+ T-cell counts and a high incidence of extrapulmonary tuberculosis and opportunistic infections such as PCP." (PMID 40510348, 2025). "The reason for this result might be that those with lower CD4 counts have low immunity and therefore develop multiple opportunistic infections and might develop immune reconstitution inflammatory syndrome (IRIS)." (PMID 38544723, 2024). "Depending upon the CD4 count, the following opportunistic infections are seen." (PMID 39050280, 2024). "In addition to improving clinical symptoms and signs, they reduce the incidence of opportunistic infections, stabilize viral loads, increase CD4+ T lymphocyte counts, prolong patient survival, and lower mortality rates." (PMID 39175814, 2024). "Hence, it opens the discussion window of pathophysiology other than high viral load-induced endothelial damage, low CD4 count-induced immune activation, or secondary triggers such as opportunistic infections." (PMID 39445270, 2024). "This systematic review and meta-analysis found that factors such as patient adherence to ART, body mass index, baseline CD4 count, disclosure, opportunistic infections, and baseline viral load count had a significant pooled impact on virological suppression in Ethiopia." (PMID 38654969, 2024).
Opportunistic infection (continued). "Duration of HIV infection (OR=0.576, 95%CI:0.444-0.747), albumin (OR=0.956, 95%CI:0.936, 0.976) and CD4+T cell counts (OR=0.999, 95%CI: 0.998,1.000) showed negative associations with opportunistic infections (P<0.05)." (PMID 39866736, 2024). "This study aimed to assess whether in clinical practice, patients are presenting with higher baseline CD4 counts, describe the incidence of opportunistic infections and the proportion that achieved viral suppression." (PMID 38299523, 2024). "MPOX disease might raise morbidity and cause prolonged illness in individuals with advanced HIV infection (CD4 < 350 cells/mm3) or with untreated HIV, resembling HIV-associated opportunistic infections." (PMID 38979508, 2024). "Absolute CD4+ T lymphocyte count is a crucial indicator of immune competence and is used to evaluate the stage of the disease, detect delayed diagnoses, determine the need for prophylaxis against opportunistic infections, and assess treatment success." (PMID 39768973, 2024). "While there is some overlap between these guidelines, special care should be taken for PWH as certain treatments may further deplete cellular immunity and prolong lower CD4+ cell counts, positioning PWH at risk for opportunistic infections." (PMID 39459894, 2024). "When CD4+ T-cell counts decline, people with chronic HIV infection who are not receiving antiretroviral therapy become susceptible to a variety of infections that are uncommon in immunocompetent hosts-hence the term "opportunistic infections" (OIs)." (PMID 39221366, 2024). "This may be due to the presence of advanced opportunistic infections, which may deplete CD4 counts and compromise immunity, or the fact that medications for co-infection treatment and ART together can contribute to double burden side effects." (PMID 38652716, 2024). "In addition, studies highlight the significant immune suppression observed in HIV/HBV/HDV co-infected individuals, particularly through reduced CD4+ cell counts, which exacerbates their vulnerability to opportunistic infections." (PMID 39599836, 2024). "Nevertheless, an overall better immunological status is desirable for any cancer patient, and patients with higher CD4 + T cell counts had a significantly prolonged time to melanoma relapse and would be less likely to develop further complications such as opportunistic infections." (PMID 39609320, 2024). "The probability of opportunistic infection greatly increases when the CD4+ T-cell count is <200/μL." (PMID 39174035, 2024). "Several factors influence surgical outcomes in HIV-positive patients, including immunological status (CD4 T-cell count), presence of opportunistic infections, white blood cell count, hematocrit levels, nutritional status (albumin levels), type of surgery, and hygiene." (PMID 39575001, 2024). "From a purely clinical perspective, patients with lower CD4 counts are at increased risk for opportunistic infections, non-communicable diseases and death." (PMID 39028735, 2024). "In our study, the individuals that received selenium supplementation experienced an increase on CD4+ T cell frequency which represent an improvement on their health status and may be protective against apparition of opportunistic infections." (PMID 39351495, 2024). "CD4 + T cells are particularly crucial in providing immune defense against opportunistic infections, which are caused by pathogens that typically do not cause disease in individuals with a healthy immune system." (PMID 38280109, 2024). "This study identified significant risk factors for opportunistic infections through multifactorial logistic regression analysis, including nutritional risk, duration of HIV infection, HbA1c levels, lymphocyte counts, albumin level, and CD4+ T cell counts." (PMID 39866736, 2024).